HGF (hepatocyte growth factor)
Diseases named in the same sentence as HGF in open-access papers (continued):
Sharing a sentence is not in itself a finding about the gene and the disease.
gastric cancer (continued). "We speculate that the MACC1 protein may induce the process of EMT in gastric cancer cells through the HGF/c-Met pathway, and consequently influences the peritoneal metastasis of gastric cancer." (PMID 24325214, 2013). "MACC1 may be involved in the development of gastric cancer through the HGF/c-Met pathway, or as an independent factor in the gastric process, or through other pathways." (PMID 24325214, 2013). "Most of HGF is derived from stromal cells in gastric cancer." (PMID 23690936, 2013). "Therefore, c-Met has been recognized as an important therapeutic target in antineoplastic strategies, and also has shown to possess predictive properties for the treatment with the monoclonal antibody to HGF in locally advanced or metastatic gastric cancer." (PMID 24223894, 2013). "Given that the HGF/MET pathway is highly activated in gastric cancer, it is biologically plau-sible that the MET S375 variant with a low affinity for HGF may reduce gastric cancer risk, which is con-sistent with our findings." (PMID 23554766, 2012). "HGF regulates Rac-1-induced ROS production through the Akt pathway and ROS regulates uPA production and invasion via MAP kinase, which provides novel insight into the mechanisms underlying the progression of gastric cancer." (PMID 19497102, 2009). "We conclude that HGF may be one of the most important factors regulating gastric cancer metastasis." (PMID 35328253, 2022). "This may indicate an important role of SDF1/HGF/VEGF in early intestinal gastric cancer spread." (PMID 35328253, 2022). "Importantly, inhibiting of tumor development by blocking GCMSCs-derived HGF may become a new target for the treatment of gastric cancer." (PMID 33718248, 2021). "Hence, we hypothesized that GCMSCs could upregulate the expression of HK2 in gastric cancer cells by secreting HGF." (PMID 33718248, 2021). "The Wnt/β-catenin, HGF/c-MET, and Ras/Erk pathways have been associated with numerous cancers and mediate EMT in gastric cancer (GC)." (PMID 32825724, 2020). "As the gene encoding the hepatocyte growth factor (HGF) receptor, MET, is a transcriptional target of MACC1, the downstream signaling pathway of HGF-c-MET maybe involved in the mechanism of the“MACC1 regulating the resistant to trastuzumab” in gastric cancer cells." (PMID 27581375, 2016). "For example, hepatocyte growth factor (HGF) siRNA was loaded into EVs after transfection of HEK293T cells, resulting in suppression of tumor growth and angiogenesis in gastric cancer." (PMID 39204374, 2024). "Gastric cancer cell‐derived exosomal EGFR promotes liver‐specific metastasis in Kupffer cells and hepatic stellate cells by enhancing HGF signalling in the liver." (PMID 38661437, 2024). "One study revealed that hepatocyte growth factor (HGF) secreted from fibroblasts was important for inducing CAF activation in surrounding normal fibroblasts and promoting the growth of gastric cancer cells." (PMID 38825636, 2024). "In summary, our review underscores the critical molecular pathways driving gastric cancer progression, including the MAPK, PI3K/AKT/mTOR, HGF/c-MET, and Wnt/β-catenin pathways." (PMID 37894443, 2023). "Further analysis showed statistical significance between healthy control serum HGF levels and intestinal IV-IVB (p = 0.03), diffuse III, IV-IVB (p = 0.01) and total diffuse (p = 0.006) gastric cancer." (PMID 35328253, 2022). "In another study, exosomes isolated from HEK-293 cells were transfected with HGF siRNA demonstrated reduced vascularization with reduction in levels of HGF and VEGF proteins in gastric cancer cells tumors compared to free siRNA." (PMID 35456698, 2022). "Our results indicate that SDF-1, HGF and VEGF are very important molecules involved in gastric cancer progression." (PMID 35328253, 2022). "The HGF-MET-signaling pathway mediates the invasive growth of different malignancies such as head and neck squamous cell carcinoma, gastric cancer, colorectal cancer, and ESCC." (PMID 34217156, 2021).
gastric cancer (continued). "The effect of HGF derived from GCMSCs on the proliferation, metastasis, and HK2 expression of gastric cancer cells was evaluated in vitro and in vivo." (PMID 33718248, 2021). "Our study focused on the integrative analyses of HGF and c-MET, and there was consistency between HGF and c-MET in terms of survival prediction, KEGG pathway enrichments and expression level in gastric cancer tissues and peritumor ones." (PMID 32788873, 2020). "Blockade of HGF/c-Met signaling system using an HGF antagonist NK4, when combined with intraperitoneal chemotherapy, suppressed gastric cancer peritoneal metastases in nude mice and enhanced survival." (PMID 32780245, 2020). "It was reported that CAFs promoted VM formation in HCC by paracrine TGF-β and SDF1; CAFs-derived HGF promoted vascularization in gastric cancer via PI3K/AKT and ERK1/2 signaling; CAFs induced VM formation in gastric cancer cells through EphA2-PI3K pathway." (PMID 33153467, 2020). "In silico analysis of the TCGA and GEO database found that HGF and c-MET mRNA expression are significantly higher in gastric cancer tissues than those in peritumor tissues." (PMID 32788873, 2020). "In summary, FBN1, FN1, HGF, MMP9, THBS1, and VCAN can be used as new target genes to observe the prognosis of gastric cancer." (PMID 33014013, 2020). "EVs overexpressing hepatocyte growth factor (HGF) siRNA drastically reduced HGF and vascular endothelial growth factor (VEGF) expression in gastric cancer." (PMID 31835327, 2019). "Different antibodies targeting MET or its ligand HGF, and tyrosine kinase inhibitors targeting MET are investigated in clinical trials with gastric cancer patients." (PMID 31557260, 2019). "Therefore, miRNAs-HGF axis could function as a novel treatment strategy for gastric cancer." (PMID 30360560, 2018). "In contrast to the HGF-dependent A549 cell line, SNU5 gastric cancer cells express high levels of constitutively phosphorylated c-Met." (PMID 26879245, 2016). "NRP-1 depletion counteracted the activation of VEGF/VEGFR2, EGF/EGFR and HGF/c-Met pathways stimulated by respective ligands, indicating that NRP-1 acts as multifunctional co-receptors in gastric cancer cells." (PMID 26795388, 2016). "al demonstrated that the HGF/c-Met pathway induces epithelial mesencymal transition (EMT), which has the potential to promote peritoneal dissemination in gastric cancer." (PMID 24325214, 2013). "c-MET, HGF, and HGF/c-MET levels were also measured in six gastric carcinomas and 33 Head and Neck (HN) carcinomas." (PMID 21283737, 2011). "In this study, we found that HGF modulates Rac-1-regulated ROS production, ROS induces the expression of uPA via the MAPK pathway, and stimulates the invasiveness of human gastric cancer cells." (PMID 19497102, 2009). "Furthermore, serum HGF levels may be of value as a tumour marker in patients with gastric cancer." (PMID 9043023, 1997). "HGF produced by tumor mesenchymal stem cells increases HK2 expression in nearby gastric cancer cells, and HK2 plays an essential role in gastric cancer cell proliferation, migration, and gastric cancer progression." (PMID 41374996, 2025). "In addition, it has been reported that an HGF-enriched condition significantly reduced the therapeutic potential of MET-TKI in MET-amplified NSCLC and gastric cancer, and additional inhibition of HGF overcame the resistance." (PMID 40299443, 2025). "Moreover, FLOT1 mediates the levels of heterotypic signaling molecules, including TNF-α, EGF, HGF, and IGF1, across various cancers, such as breast, prostate, and gastric cancer, and oral squamous cell carcinoma." (PMID 40335491, 2025). "Further investigations revealed that stimulation with HGF did not significantly enhance the self-renewal ability of gastric cancer cells through the TAZ gene." (PMID 38634107, 2024).
gastric cancer (continued). "Other studies in gastric cancer cell lines showed that anti-HGF inhibited further cell growth and that HGF could be produced by gastric fibroblasts, the invasiveness of which could be promoted by MET expression on gastric cancer cells." (PMID 37046637, 2023). "MACC1 can activate hepatocyte growth factor (HGF), and the activated HGF can easily bind to c-MET, which promote the phosphorylation of c-MET, thereby inducing the proliferation and invasion of gastric cancer." (PMID 35874635, 2022). "Mechanistically, MACC1 may contribute to cancer progression via the MACC1/hepatocyte growth factor (HGF)/c-Met axis, as has been reported for ovarian cancer, gastric cancer, and HCC." (PMID 33425885, 2020). "Similar to ovarian and gastric cancers in invasion section, blockade of the HGF receptor pathway by administration of recombinant NK4, a four-kringle fragment of HGF which functions as its antagonist, inhibits growth, invasion, and distant metastasis of orthotopically implanted PDA cells." (PMID 32780245, 2020). "The cBioportal Web tool was utilized to explore HGF and c-MET gene alterations in gastric cancer." (PMID 32788873, 2020). "HGF is not usually detected in the CM from gastric cancer cells, thus, it can affect the invasive capabilities of SGC cells in a paracrine fashion." (PMID 33178597, 2020). "In addition, miR-34a downregulated Snail directly or through inhibition of HGF/c-Met, which promoted EMT in gastric cancer." (PMID 32219093, 2020). "Overexpression of HGF mRNA and/or protein, MET mRNA and c-MET protein have been recorded in 20-30%, and 40-70% samples of gastric cancer patients, respectively 14, 28, which were higher than the proportion of gastric cancer dataset based on TCGA database." (PMID 32788873, 2020). "E-cadherin, HGF/c-MET, ARL4C, integrins and other ECM protein/cell receptor interactors, and EMT-related proteins all contribute to cell detachment process in ovarian and gastric cancers." (PMID 32780245, 2020). "To date, no drug targeting the HGF/MET pathway has been approved for gastric cancer treatment, but antibodies or tyrosine kinase inhibitors against MET are currently being investigated in clinical trials (see introduction)." (PMID 31557260, 2019). "The anti-HGF antibody rilotumumab did not improve the clinical outcome in MET-positive advanced gastric cancer or gastroesophageal junction (GEJ) cancer in a phase III study (RILOMET-1)." (PMID 31557260, 2019). "Importantly, they confirmed overexpression of HGF and c-MET are correlated with peritoneal dissemination and poor prognosis in gastric cancer." (PMID 30360560, 2018). "There is few report that described the relationship between serum HGF and HER2 in gastric cancer." (PMID 26716644, 2016). "Taken together, activation of HGF/MET pathway were strongly associated with the resistance to HER2 inhibitor and this mechanism were more frequently observed in HER2-positve gastric cancer patients compared with HER2 negative patients." (PMID 26716644, 2016). "AFP-producing gastric cancer highly expresses VEGF-C, SALL4, and c-Met/HGF." (PMID 27995033, 2016). "The results from two phase III RILOMET-1 and MET Gastric studies were negative, and the development of HGF/MET-targeted monoclonal antibodies for the first-line treatment of advanced gastric cancer has been nearly stopped." (PMID 26880889, 2016). "In addition, HOTAIR also epigenetically downregulates miR34a by binding to PRC2 to activate its target genes C-Met (HGF/C-Met/Snail pathway) and Snail, thereby promoting EMT in advanced stages of gastric cancer." (PMID 26136075, 2015). "However, the rate of the aberrant increase in HGF levels was significantly higher than that of any other tumour markers, including CEA, CA19-9 and CA125, in primary gastric cancer patients." (PMID 9043023, 1997).
gastric cancer (continued). "Recently, the significant therapeutic effect of SRI31215, a novel small molecule inhibitor of pro-HGF activation (inhibitor of hepsin, matriptase and HGF activator: similar function with HAIs), has been reported in MET-amplified non-small cell lung and gastric cancer cells." (PMID 40299447, 2025). "Our results indicate that SDF-1, HGF and VEGF may promote gastric cancer progression." (PMID 35328253, 2022). "In conclusion, SDF-1, HGF and VEGF may promote gastric cancer progression." (PMID 35328253, 2022). "Indeed, joint overexpression of DRs and their ligand often promotes aggressive tumor progression, as was, for example, shown for HGF and c‐MET in NSCLC or gastric cancer, suggestive of a positive selection for ligand‐induced rather than ligand‐independent signaling." (PMID 34542930, 2021). "The topmost molecular network in the intestinal subtype on IPA network analysis showed increased expression of SULF1, HGF, SPARC, SERPINH1, and IGFBP7, which have been shown to contribute to the growth and survival of tumor cells, tumor invasion, metastasis, and poor survival in gastric cancer." (PMID 34885041, 2021). "Although BMS-777607 has been found to inhibit cell growth in a xenograft model of gastric carcinoma and to suppress the metastatic phenotype of HGF-induced prostate cancer, we did not observe a significant effect of BMS-777607 on the viability of either CE81T or KYSE-70 ESCC cells." (PMID 31781483, 2019). "We measured serum concentrations of hapatocyte growth factor (HGF) in patients with gastric cancer and compared these with the histological findings and conventional tumour markers, including CEA, CA19-9 and CA125, for evaluation of the significance of serum HGF levels as a tumour marker." (PMID 9043023, 1997). "Furthermore, in gastric cancer (GC), YBX3 regulates Hepatocyte Growth Factor (HGF)-mediated cellular proliferation and metastasis." (PMID 41213937, 2025). "As a consequence of receptor over-expression due to gene amplification, human gastric carcinoma GTL-16 cells feature a constitutively active MET, highly phosphorylated in the absence of HGF." (PMID 35351166, 2022). "In vitro, EVs from SGC-7901 gastric cancer cells delivered GFP tagged EGFR to non-cancerous primary mouse liver cells resulting in a 3-fold increase in both EGFR expression and HGF secretion." (PMID 33143170, 2020). "c-MET, HGF, and HGF-c-MET complexes in FFPE specimens of human Non-Small Cell Lung Cancer (NSCLC), Gastric Cancer, Head and Neck Squamous Cell, and Head and Neck Non-Squamous Cell carcinomas." (PMID 21283737, 2011). "Although rilotumumab (an anti-HGF antibody) and onartuzumab (an anti-MET antibody) have not been found to confer survival benefit in non-small cell lung or gastric cancers, rilotumumab reportedly showed survival benefit when used with panitumumab in a phase II trial." (PMID 27296289, 2016).
liver fibrosis (121 papers, 2007 to 2026). "The Fc-based HGF mimetic alleviated liver fibrosis in a mouse model fed a choline-deficient high-fat diet, which induces hepatic features of non-alcoholic steatohepatitis, including fibrosis, showcasing its potential as a therapeutic intervention." (PMID 39108737, 2024). "Our group has demonstrated that high serum HGF levels are associated with greater liver fibrosis in HCV-infected patients." (PMID 33972651, 2021). "Treatment of fibrotic livers with two injections of vector encoding mMMP-9 gene or combined HGF/mMMP-9 genes resulted in significant reduction of liver fibrosis by 41 percent and a median fibrosis score grade of 1.0 (IQR: 1.0) indicating mild fibrosis." (PMID 25380300, 2014). "Our investigation revealed that elevated HGF secretion was associated with liver fibrosis." (PMID 40419692, 2025). "Therefore, the release of HGF in the parenchyma of damaged livers could be associated with the ability of MSCs to reverse the progression of liver fibrosis." (PMID 33425900, 2020). "Numerous studies have demonstrated that HGF exerts therapeutic effects on diseases such as myocardial infarction, liver fibrosis, renal fibrosis, focal cerebral ischemia, and pulmonary fibrosis." (PMID 40799816, 2025). "In hepatic fibrosis, inhibition of miR-26a-5p enhances hepatocyte growth factor (HGF) production, an antagonist of TGF-β–induced fibrosis." (PMID 41407811, 2025). "Hepatocyte NRP-1 expression increased significantly during liver fibrosis and was positively correlated with HGF/c-Met expression and fibrosis severity." (PMID 40419692, 2025). "HCV infection upregulates miRNA expression, downregulates Smad7 and HGF, have a role in development of liver fibrosis." (PMID 39185567, 2025). "We investigated the role of hepatocyte-specific NRP-1 deletion in liver fibrosis progression and its relationship with the HGF/c-Met pathway." (PMID 40419692, 2025). "Studies have shown that MSCs overexpressing HGF improve liver regeneration in a rat model of liver fibrosis." (PMID 39259445, 2024). "Many studies had demonstrated that hepatocyte growth factor (HGF) serves as a significant inhibitor of liver fibrosis." (PMID 38874773, 2024). "Hepatocyte growth factor (HGF) is clinically significant in liver fibrosis, hepatocyte regeneration post-inflammation, and post-transplant liver regeneration." (PMID 39845086, 2024). "Ursodeoxycholic acid (UDCA), for instance, can alleviate liver fibrosis by promoting liver regeneration through the activation of the ID1-Wnt Family Member 2 (WNT2)/hepatocyte growth factor (HGF) pathway." (PMID 39199400, 2024). "In the present study, we described the role of Gab1 in the development of liver fibrosis via HGF/c-Met signaling axis." (PMID 38935609, 2024). "The results of this study showed the synergistic ameliorative and regeneration ability of ADMSCs, PRP, and HGF on cholestasis-induced liver fibrosis/cirrhosis, which have the potential to be put into practice." (PMID 38474368, 2024). "Several papers reported that HGF secreted by genetically modified MSCs showed a therapeutic effect in murine models of myocardial infarction, radiation-induced intestinal injury and liver fibrosis." (PMID 38397096, 2024). "Human platelets also attenuate liver fibrosis in severe combined immunodeficiency (SCID) mice by secreting HGF that inhibits HSC activation, upregulates MMPs, and restrains hepatocyte apoptosis." (PMID 38138981, 2023). "The capacity of CYLD to antagonise HDAC7‐mediated repression of HGF expression limited hepatic fibrosis, suggesting a potential role for HDAC7 as a switch that enables gene expression upon liver injury." (PMID 35303381, 2023). "In particular, he demonstrated that the controlled administration of hepatocyte growth factor (HGF) allowed efficient recovery from liver fibrosis in experimental mice by stimulating liver regeneration." (PMID 37242741, 2023).